ABCB5 (ATP binding cassette subfamily B member 5)
Description:
Energy-dependent efflux transporter responsible for decreased drug accumulation in multidrug-resistant cells. Specifically present in limbal stem cells, where it plays a key role in corneal development and repair (By similarity).
Synonyms: EST422562; ABCB5beta; ABCB5alpha
Tractability: Small molecule: it belongs to a druggable protein family. Antibody: UniProt places it where antibodies can reach, with high confidence; its Gene Ontology location is reachable by antibodies, with high confidence; UniProt predicts a signal peptide or a membrane-spanning region. PROTAC: ubiquitination databases record sites on it.
Target class: ATP-binding cassette; ABCB subfamily; Transporter; Primary active transporter
Safety:
Unwanted effects reported when the protein is acted on. In parentheses: how it was acted on, where the effect was seen, and who reports it.
haloperidol-induced toxicities (source: ClinPGx)
Gene: Protein-coding gene on chromosome 7 (20,615,667 to 20,777,038, forward strand). Ensembl gene ENSG00000004846.
Subcellular location: Cell membrane
Pathways (Reactome):
Transport of small molecules: ABC-family protein mediated transport
Gene Ontology:
Molecular function: ABC-type xenobiotic transporter activity; efflux transmembrane transporter activity; ATPase-coupled transmembrane transporter activity; ABC-type transporter activity; ATP binding; ATP hydrolysis activity
Biological process: regulation of membrane potential; transmembrane transport; eye development; xenobiotic transport
Cellular component: plasma membrane; apical plasma membrane; membrane
Genetic constraint (gnomAD): Loss-of-function variants: 130 observed, 127.67 expected, observed/expected ratio (o/e) 1.02, 90% interval 0.88 to 1.18. The upper end of that interval is the gene's LOEUF score, 1.18, which puts it in group 5 of 6, group 1 being the genes least tolerant of losing a copy. Missense variants: 1,617 observed, 1,405.5 expected, observed/expected ratio (o/e) 1.15, 90% interval 1.1 to 1.2. Synonymous variants: 569 observed, 501.43 expected, observed/expected ratio (o/e) 1.13, 90% interval 1.06 to 1.22.
Homologues: Orthologues: chimpanzee ABCB5 (98% identical), macaque ABCB5 (96% identical), dog ABCB5 (86% identical), rabbit ABCB5 (84% identical), guinea pig ABCB5 (81% identical), pig ABCB5 (79% identical), rat Abcb5 (78% identical), mouse Abcb5 (78% identical), tropical clawed frog abcb5 (57% identical), Caenorhabditis elegans pgp-9 (42% identical), Caenorhabditis elegans pgp-1 (41% identical), Caenorhabditis elegans pgp-6 (37% identical), and 7 more. Paralogues in human: ABCB1 (55% identical), ABCB4 (55% identical), ABCB11 (47% identical), ABCB10 (18% identical), ABCB9 (17% identical), ABCB8 (16% identical), TAP2 (16% identical), TAP1 (15% identical), ABCB6 (15% identical), ABCB7 (13% identical).
Diseases named in the same sentence as ABCB5 in open-access papers:
ABCB5 is named in the same sentence as 83 diseases in open-access papers, as found by Europe PMC text mining. Sharing a sentence is not in itself a finding about the gene and the disease. The quoted sentences say what the papers report.
melanoma (163 papers, 2006 to 2026). A malignant, usually aggressive tumor composed of atypical, neoplastic melanocytes. "Previous studies have demonstrated that ABCB5 overexpression in CSCs associated with tumor progression, chemoresistance and disease relapse in malignant melanoma patients." (PMID 40746888, 2025). "ABCB5 encodes a full transporter (known as ABCB5FL, ABCB5.ts, expressed in the testis and prostate) and a half transporter (ABCB5β, expressed in melanocytes and melanoma)." (PMID 41020871, 2025). "ABCB5 is implicated in the survival of melanoma-initiating cells, which are often resistant to therapies, including RT." (PMID 40867277, 2025). "It has been shown that several mutations in ABCB5 promote the proliferation and invasive capacities of melanoma cells." (PMID 37958830, 2023). "ABCB5, which is also associated with therapeutic resistance, provides a promising therapeutic target for melanoma." (PMID 36431795, 2022). "Recently, we showed that MCAM/MUC18/CD146 and ABCB5 can serve as melanoma-specific-targets in the selection of highly primitive circulating melanoma cells, and constitute putative proteins associated with disease spreading progression." (PMID 34830300, 2021). "For example, a marker known as ABCB5 has been found to be significantly associated with melanoma drug resistance." (PMID 34805163, 2021). "The ABCB5 trans-membrane transporter is strongly associated with melanoma genesis, stem cell maintenance, metastasis, and chemoresistance." (PMID 34830300, 2021). "Herein, we described how CMC subpopulations expressing MCAM, as melanoma-associated antigen and/or ABCB5, as melanoma-initiating marker, display distinct gene profiles." (PMID 32548126, 2020). "Human tumorigenic melanoma reveals that a minority of cells expresses the ABCB5 cell membrane–associated transporter." (PMID 32548126, 2020). "It has been demonstrated that NF-κB activity is preferentially maintained in a subpopulation of ATP-binding cassette member B5 (ABCB5)-positive melanoma cells, which exert more metastatic phenotype than ABCB5-deficient cells." (PMID 32466509, 2020). "Here, in this study, we report on CTC subpopulations expressing either MCSP, a melanoma-associated marker, or ABCB5, a melanoma-initiating marker, and show that they display distinct transcriptomic profiles." (PMID 30769764, 2019). "Within these constraints, the model was found to reliably mimic melanoma cell invasion into the dermal compartment, drug-induced selection of ABCB5-expressing melanoma cells, and loss of melanoma-induced keratinocyte differentiation." (PMID 31035967, 2019). "This is particularly important as, except for CALU, the remaining seven EMT genes found to be up-regulated in ABCB5-enriched CTC fractions have been previously associated with melanoma metastasis, invasion, and/or tumour growth." (PMID 30769764, 2019). "Our previous studies have shown that ABCB5 was associated with a poor clinical outcome in melanoma patients with positive sentinel lymph nodes." (PMID 29929490, 2018). "The results showed that SK-MEL-2 cells have a lower ABCB5 expression than the other three melanoma cell lines with BRAF mutation." (PMID 29929490, 2018). "ABCB5 was reported to be associated with resistance to several chemotherapeutic agents for melanoma, such as doxorubicin, dacarbazine, and temozolomide." (PMID 29929490, 2018). "We also compared the expression of ABCB5 in the three parent cells that have BRAF mutation with that of another melanoma cell line, SK-MEL-2, which has wild-type BRAF expression." (PMID 29929490, 2018). "Similar reports are available ABCB5 which is associated with MDR resistance in human malignant melanomas patients." (PMID 28785557, 2017). "They then concluded that MART-1/ MLANA and ABCB5 are helpful in following high-risk melanoma patients confirming that MCAM/MUC18/CD146 expression is associated with poorer outcome in stage IV disease." (PMID 28280601, 2017).
melanoma (continued). "This is mainly caused by a preferential enrichment of CTCs expressing ABCB5 over the rest of the melanoma CTCs expressing other markers, particularly RANK expressing CTCs." (PMID 28978038, 2017). "In contrast, other groups have shown that hypoxia induces downregulation of miR-340-5p expression which is responsible for upregulation of melanoma-stem cell associated marker, ABCB5." (PMID 28137308, 2017). "Consistent with a possible functional role of ABCB5 in the maintenance and/or biological activity of melanoma-initiating cells, ABCB5 genetic variation was associated with melanoma risk." (PMID 29156643, 2017). "The findings presented here describe a number of melanoma stem cell markers (e.g. ABCB5, JARDIB, and CD271) that are linked to UV-miRNAs in the irradiated melanocytes of patients." (PMID 27149382, 2016). "In a preliminary study, we explored molecular targeting of melanoma-initiating stem-like cells using ABCB5 markers previously shown to be associated with metastatic disease progression in melanoma patients." (PMID 24335964, 2013). "ABCB5 has been shown to be expressed in a subset of melanoma cells and is associated with tumour formation, metastasis and resistance to treatment." (PMID 22978632, 2012). "Their abundance in clinical melanoma specimens correlates positively with the neoplasic progression suggesting that ABCB5 expression is associated with tumor aggressiveness." (PMID 22675422, 2012). "Another variant of this transporter, ABCB5 beta posses a “half-transporter-like” structure and is expressed in melanoma stem cells, normal melanocytes, and other types of pigment cells." (PMID 21298007, 2011). "The fact that ABCB5 beta has been implicated in doxorubicin transport in melanoma cells and also in hepatocellular carcinoma cells lends support to this theory." (PMID 21298007, 2011). "Furthermore, elevated ABCB5 expression has been linked to tumor progression in melanoma, indicating an association with increased tumor aggressiveness." (PMID 40445912, 2025). "This suggests that ABCB5 could serve as a valuable prognostic factor in melanoma, helping to identify patients at higher risk for aggressive disease." (PMID 40867277, 2025). "Furthermore, sequencing showed that SNPs of ABCB5 were associated with decreased melanoma risk (i.e., rs10231520, rs17817117, and rs2301641)." (PMID 39267923, 2024). "Besides CD146, the ABCB5 trans-membrane transporter is strongly associated with melanoma genesis, stem cell maintenance, metastasis, and chemoresistance." (PMID 37511550, 2023). "In addition to CD146, the transmembrane transporter ABCB5 is strongly associated with melanoma genesis, stem cell maintenance, metastasis, and chemoresistance." (PMID 37511550, 2023). "ABCB5 is one of the most frequently mutated genes in melanoma." (PMID 37958830, 2023). "Nevertheless, a variety of markers associated with some melanoma-specific cell-surface epitopes have been proposed, such as CD146 and MSCP/NG2, (melanoma-associated chondroitin sulfate) together with stem cell markers such as ABCB5 (ATP-binding cassette-subfamily member B) and CD271." (PMID 34830300, 2021). "In combination with negative selection for leukocyte specific markers, various markers are used to detect melanoma cells in peripheral blood, including CD146, melanoma-associated chondroitin sulfate proteoglycan, ATP-binding cassette subfamily B member 5, CD271, and receptor activator of NF-κB." (PMID 33731038, 2021). "The association of an ABCB5-expressing melanoma subset with tumorigenic growth, typical of the VGP, supports the rationale that CMCs derive from rare cancer subpopulations that may potentially initiate metastases." (PMID 32548126, 2020). "Interestingly, expression of ABCB5 demonstrated to associate with melanoma initiation, chemoresistance or refractory disease in colorectal cancer and haematological malignancies." (PMID 32783366, 2020).
melanoma (continued). "However, we found in a previous study that CTCs more commonly express melanoma-initiating markers, such as the ATP-binding cassette sub-family B member 5 (ABCB5) than melanoma-associated markers, such as MCSP." (PMID 30769764, 2019). "Furthermore, the induction of differentiation of melanoma cells was associated with a decreased ABCB5 expression." (PMID 29156643, 2017). "Moreover, it has also been reported that the amplification of ABCB5 is a predisposing factor for melanoma development which further emphasize the specific role of stem cells in melanoma growth." (PMID 28137308, 2017). "Metabolic profiles for two groups of human G3361 melanoma cells were compared, i.e. wildtype melanoma cells with intact ABCB5 expression (ABCB5-WT) and corresponding melanoma cell variants with inhibited ABCB5 expression, through shRNA-mediated gene knockdown (ABCB5-KD)." (PMID 27560924, 2016). "Furthermore, depletion using a siRNA that targets a short variant of ABCB5 was shown to sensitize melanoma cells to the camptothecin cytotoxic effect." (PMID 22675422, 2012). "The function of ABCB5 is unfortunately also unknown, but it is a biomarker that predicts the recurrence of oral squamous cell carcinoma and is linked to chemoresistance in melanoma, liver cancer, breast cancer, and colon cancer." (PMID 39861164, 2025). "Interestingly, specific SNPs in ABCB5 have been reported to associate with melanoma risk." (PMID 32783366, 2020). "ABCB5 has been identified as a marker of melanoma-initiating cells, and its expression is induced by β-catenin." (PMID 40558548, 2025). "ABCB5 is expressed in different tissues, including melanocytes, melanoma cells, testis, mammary tissue, and retinal pigmented epithelium." (PMID 41020871, 2025). "In this previous study, giant cells were proliferative, chemo-resistant and expressed melanoma stem cell markers ABCB5 and CD133." (PMID 40754577, 2025). "In melanoma, subpopulations of ABCB5-expressing cells increase their tumorigenicity and display properties similar to those of cancer stem cells (CSCs), which contribute to cancer initiation, progression, metastasis, recurrence, and resistance to chemotherapy." (PMID 41020871, 2025). "We identified the melanoma cell adhesion molecule (MCAM/MUC18/CD146) and the ATP binding cassette subfamily B member 5 (ABCB5) as melanoma-specific targets to isolate and purify a highly primitive and aggressive subset of circulating melanoma cells (CMCs)." (PMID 40332096, 2025). "Another putative CSC marker, the transmembrane transporter ABCB5, plays a significant role in radiation resistance and chemoresistance in melanoma." (PMID 40867277, 2025). "DDX43 regulates RAS protein expression and AKT activation, prevents the expression of PML in ABCB5+ malignant melanoma-initiating cells, and plays a critical role in the male sex differentiation of channel catfish (Ictalurus punctatus)." (PMID 41157636, 2025). "The stemness gene Kruppel-like factor 4 (KLF4) is also upregulated by CD133 in this NF-κB pathway, in agreement with our previous results showing upregulation of other stemness genes such as Oct4 and ABCB5 in CD133(+)-enriched BAKP melanoma stem cells." (PMID 38727313, 2024). "G3361 melanoma cells expressing ABCB5 accumulated less doxorubicin and blockade of ABCB5 with the same anti-ABCB5 mAb increased doxorubicin uptake." (PMID 39267923, 2024). "shRNA against ABCB5 or anti-ABCB5 mAb on G3361 melanoma cells decreased cancer cell survival to dacarbazine, paclitaxel, teniposide, docetaxel, etoposide, doxorubicin, and vincristine." (PMID 39267923, 2024). "ABCB5 marked a distinct cell population from CD133+ G3361 melanoma cells, consisting of mononucleated and multinucleated cells." (PMID 39267923, 2024). "ABCB5(+) malignant MSCs showed a higher metastatic potential compared to ABCB5(-) melanoma subpopulation." (PMID 39611156, 2024).
melanoma (continued). "In particular, monoclonal antibodies directed at ABCB5 were reported to reverse melanoma cell resistance to doxorubicin; however, further investigations are warranted to confirm these data." (PMID 39199632, 2024). "In a murine xenograft model of melanoma, temozolomide led to the selection of ABCB5-expressing cells." (PMID 39267923, 2024). "Based on these observations, further studies are needed to confirm the reliability of the MITF/ABCB5 axis as a marker of melanoma cell stemness." (PMID 39199632, 2024). "ABCB5+ melanoma cells purified by immunomagnetic selection and 3C2-1D12 antibody had immunomodulatory functions including inhibition of IL-2 secretion and induction of IL-10 secretion, which affected antitumor immunity by inhibiting T-cell activation." (PMID 39267923, 2024). "In melanoma or retinoblastoma cell culture, ABCB5 protein (600-401-A77 antibody from Rockland) or mRNA expression did not correlate with CD271 or CD133 expression." (PMID 39267923, 2024). "Further, all published data on ABCB5 expression in melanoma CSCs rely on antibodies to isolate ABCB5+ cells." (PMID 39267923, 2024). "RT-qPCR identified ABCB5 as a marker of circulating melanoma cells in the peripheral blood of patients and its expression correlated with disease progression and recurrence." (PMID 39267923, 2024). "ABCB5+ melanoma cells were reported to express endothelial/proangiogenic molecules as well as specific VM markers, such as VEGF and its receptors, Tie2 and VE-cadherin." (PMID 39199632, 2024). "Specifically, MITF, the transcription factor known to sustain the expression of ABCB5, is highly expressed in differentiated melanoma cells and this correlates with high levels of ABCB5." (PMID 39199632, 2024). "Treatment with 5 μM doxorubicin resulted in increased ABCB5 mRNA expression in three melanoma cell lines (i.e., A375, 1205Lu, and DMBC8)." (PMID 39267923, 2024). "It has also been reported that melanoma cells with a high ABCB5 expression exhibit an elevated metastatic potential both in vitro and in vivo." (PMID 37958830, 2023). "According to the literature, the ABCB1/Pgp transporter is preferentially expressed in stem cell-like human melanoma cells, as is ABCB5." (PMID 38136555, 2023). "ABCB5 was also reported to be a marker of skin progenitor cells and melanoma stem cells and to mediate anthracycline resistance." (PMID 37958830, 2023). "The subcellular localization of ABCB5β, which appears to be the main ABCB5 isoform with putative transport activity expressed in melanoma cells, has remained unclear, primarily due to concerns about the reliability of anti-ABCB5 antibodies." (PMID 37958830, 2023). "In this preliminary translational study, to our knowledge, we are among the first reporting a pilot EMT gene profile of CD45−CD146+ABCB5+ CMCs obtained from advanced melanoma patients at onset and then both in disease progression and clinical remission status." (PMID 37511550, 2023). "Our recent studies demonstrated that the acquisition of CD146 and ABCB5 as melanoma-specific targets allows the isolation of highly primitive rare stem/mesenchymal CMCs (CD45−CD146+ABCB+) associated with disease progression." (PMID 37511550, 2023). "Adenosine triphosphate ATP-binding cassette (ABCB5), as an ABC transporter, has shown linked to the development of drug resistance in many kinds of cancers, such as melanoma, human retinoblastoma, and acute leukemia." (PMID 36790659, 2023). "Herein, we characterize cells expressing MIC markers (CD20, CD24, CD133, Sca-1, ABCB1, ABCB5, ALDHhigh) in the B16-F10 murine melanoma cell line." (PMID 35408953, 2022). "This is consistent with our previous findings showing that CSV and ABCB5 are highly expressed in CTCs isolated from melanoma patients." (PMID 35326747, 2022). "Given that ABCB5 plays a key role in melanoma growth and the promotion of melanoma metastases, silencing this gene is crucial in inhibiting metastasis development." (PMID 36431795, 2022).